MET (MET proto-oncogene, receptor tyrosine kinase)
Diseases named in the same sentence as MET in open-access papers (continued):
Sharing a sentence is not in itself a finding about the gene and the disease.
tumor (continued). "Overall, these results demonstrate the substantial efficacy of combined MET and EGFR inhibition in abrogating downstream RTK signaling, reducing tumor progression, and reducing tumor response variability." (PMID 27655711, 2016). "We identified crizotinib, a MET and ALK inhibitor, as a potent inhibitor of NF2-null Schwann cell proliferation in vitro and tumor growth in vivo." (PMID 27363027, 2016). "Another anti-c-MET mAb that blocks ligand binding, MetMab (ornatuzumab, formerly OA5D5), is an engineered monovalent antibody that has been shown to inhibit tumor growth in animal models by more than 95 percent." (PMID 28536400, 2015). "Addition of HGF induced MET phosphorylation, leading to the activation of AKT and ERK, and tumor proliferation, confirming that HGF acts mainly as a paracrine factor in HNSCC cells." (PMID 26319934, 2015). "For both liver regeneration and spontaneous HCC development, there is an inclusive requirement for MET expression, and when HGF induces autocrine activation, the tumor displays sensitivity to a small-molecule MET inhibitor." (PMID 28536405, 2015). "Tumor samples from 99 patients with mGE cancer were analyzed as follows: NGS (N = 56), FISH for MET amplification (N = 65), IHC and/or FISH for HER2 (N = 87)." (PMID 26082439, 2015). "HGF and c-MET are key players in the tumor-stroma interactions, and HGF/c-MET signaling is strongly involved in tumor growth and progression, angiogenesis, and metastasis in many human cancers." (PMID 28536400, 2015). "Because Foretinib is a potent inhibitor of c-MET, this drug suppressed different c-MET-activated cell lines and reduced tumor growth in different animal studies." (PMID 25909285, 2015). "Tyrosine kinase MET is the receptor for hepatocyte growth factor (HGF/SF) and interaction between MET HGF/SF can induce scattering and migration of (tumour) progenitor cells." (PMID 25673052, 2015). "Amuvatinib (MP470) inhibits PDGFR, c-Kit, and c-MET in preclinical studies: MP470 combined with erlotinib inhibits prostate cancer cell proliferation and tumor xenograft growth, and MP470 treatment sensitizes glioblastoma cells to radiotherapy in mice." (PMID 28536400, 2015). "To confirm that the effects observed on tumor xenografts were indeed mediated by PHA665752, we studied the phosphorylation status of MET in harvested tumors by Western blot analysis." (PMID 26413215, 2015). "The same work also showed that tivantinib inhibited constitutive p-MET and HGF-induced p-MET in several type of tumor cells with an IC50 of 100 to 300 nM." (PMID 26458953, 2015). "RNA expression analysis detected increased expression of MET and NOTCH1 compared to both normal controls and tumor expression data from a range of malignancies publicly available from The Cancer Genome Atlas (TCGA)." (PMID 25798586, 2015). "The activation of the receptor tyrosine kinase c-MET in cancer correlates with poor prognosis, where aberrantly active c-MET triggers tumor growth, angiogenesis and metastasis." (PMID 29147412, 2015). "When investigating differential expression of four major known oncogenes in GC, we found that MET (p = 0.00) and ERBB2 (p = 0.00) were differentially expressed between normal and tumor tissues." (PMID 26296973, 2015). "Notably, [18F]FLT PET scans in NSCLC tumor-bearing mice have demonstrated their utility in identifying TKI-resistant tumors, which harbor the most frequently encountered mutations associated with TKI resistance, i.e., the secondary T790M mutation and MET amplification." (PMID 25853010, 2015). "Evidence indicate that the two signaling pathways, integrin/ECM and HGF/c-MET, cooperate synergistically to induce FAK activation in an adhesion-dependent manner, leading to enhanced cell adhesion and motility of tumor cells." (PMID 28536400, 2015). "Within HCC tumours, activated HSC have been found to initiate signalling pathways downstream of c-MET, including NF-κB and ERK leading to tumour proliferation and migration." (PMID 26013123, 2015).
tumor (continued). "We further noticed that cell proliferation was also downregulated in tumor samples as reflected by PCNA staining, which is probably due to the inhibition of proliferative pathways such as MET signaling." (PMID 26384345, 2015). "Correlations between increased c-MET and HCC tumour size or invasiveness of HCC have been reported in some studies." (PMID 26013123, 2015). "By using KCI-10-40X1, a PDX model derived from a GBM patient with EGFRamp, we found that a combination of V-4084 and erlotinib inhibited KCI-10-X1/erl-res tumor growth and provide additional evidence to treat GBM EGFRamp patients targeting both EGFR and MET." (PMID 26381735, 2015). "The c-MET and PIK3CA expression levels were significantly higher in 32 (78.0%) and 31 (73.8%) tumor tissues compared with adjacent non-tumor tissues (P = 2.20 × 10−5 and P = 1.00 × 10−3 respectively)." (PMID 26334097, 2015). "Considering the relevant role of c-MET in angiogenesis, activated c-MET is considered as adjuvant pro-metastatic gene for many tumour types." (PMID 26459369, 2015). "This phenomenon, besides highlighting the importance of the tumor microenvironment, further confirms that fibroblast-derived HGF/c-MET signaling is involved in resistance to chemotherapy reagents." (PMID 26090722, 2015). "miR-1 can target the MET, Slug and PI3KCA to inhibit proliferation and metastasis of different types of tumor cells." (PMID 26497855, 2015). "In summary, our study demonstrates that miR-34c is downregulated in NPC, and miR-34c can suppress tumor growth and metastasis in NPC in vitro and in vivo by targeting MET." (PMID 25611392, 2015). "But the small amount of MET-amplified cells can be expanded by the selective pressure of anti-EGFR moAbs and they can induce acquired resistance, as they become the leading tumor cell population." (PMID 26318427, 2015). "Recent clinical studies have reported a promising therapeutic impact of crizotinib, an ATP-competitive inhibitor of ALK/MET activity, in the treatment of ALK- and/or MET-positive tumours." (PMID 26445453, 2015). "Taken together, these studies highlight that HGF and aberrant c-MET signalling have a critical role in mediating the bi-directional crosstalk between HSC and tumour cells during hepatocarcinogenesis." (PMID 26013123, 2015). "RT-PCR analysis performed in a panel of 6 RMS tumours (3 ARMSs and 3 ERMSs) confirmed that ALK and MET mRNAs are expressed at significantly higher levels in ARMS compared to ERMS." (PMID 26445453, 2015). "Addition of HGF or EGF phosphorylated MET or EGFR, respectively, and demonstrated phosphorylation of Akt and ERK1/2 as well as increased tumor cell viability." (PMID 26496080, 2015). "The proto-oncogene c-MET is a transmembrane tyrosine kinase cell surface receptor for hepatocyte growth factor (HGF), which is mainly involved in cell proliferation and tumor expansion." (PMID 24884990, 2014). "It suppresses MET and VEGFR2 signaling, rapidly inducing apoptosis of endothelial and tumor cells, resulting in tumor regression." (PMID 25520915, 2014). "On the basis of the alterations identified in the tumor samples, a second targeted agent from a list of MEK, CDK4/6, FGFR, PI3K, and c-MET inhibitors will be added to the regimen." (PMID 25344914, 2014). "In MET-dependent preclinical models, it inhibited the growth of both HGF-activated and constitutively phosphorylated tumor cell lines." (PMID 28548076, 2014). "Tumor sections from vehicle control, ARQ 197, GDC-0980 and combination treated mice were immunostained with p-MET, total MET, CD31 and p-AKT." (PMID 25221930, 2014). "While MET amplification is relatively common in GEC cell lines, it is has typically been observed in <5% of patient tumor samples." (PMID 24930887, 2014).
tumor (continued). "Our results show that co-administration of c-MET (Crizotinib) and VEGFR2 (Axitinib) inhibitors suppressed tumor growth and maintained bone phenotype." (PMID 25277255, 2014). "In these studies, only the simultaneous blockade of both MET and EGFR effectively impaired tumor growth in vivo." (PMID 24811491, 2014). "Interestingly, the uptake of [11C]-methionine correlates with Ki-67 and proliferating cell nuclear antigen expression and with microvessel count in proliferating cells, suggesting that [11C]-MET uptake may represent a biological marker for tumour proliferation and neoangiogenesis." (PMID 24649372, 2014). "Hepatocarcinoma tumor cells release HGF, which stimulates MET activity, and MET activation in cell amplification promotes activation of PI3K/Akt and ERK signaling." (PMID 25162296, 2014). "Utilizing early progenitors isolated from NSCLC cell lines and fresh tumor tissues, we observed robust overexpression of PAX8, MET, and RON." (PMID 24628993, 2014). "By using a phosphoproteomic approach in SCLC NCI-H69 cells, several downstream c-MET signaling transducers were identified, such as FAK, AKT, ERK1/2 and S6 kinase, involved in tumor invasion." (PMID 25314153, 2014). "This occurred in only 1 of 7 (15%) identified MET amplified FFPE samples; the true rate at which this observed tumor evolution occurs with respect to MET amplification is an area of active research in our laboratory." (PMID 24983965, 2014). "Authors did not identify any relationship of treatment outcome with biomarkers including c-MET gene amplification, c-MET, p-c-MET and HGF expression in tumor." (PMID 24216699, 2013). "In conclusion, we demonstrated that despite tumor progression after treatment with EGFR-TKIs, NSCLCs with MET amplification are still dependent on EGFR signaling." (PMID 24167634, 2013). "Later, amuvatinib inhibition of MET activity was found to lead to reduction of RAD51 expression and to radiosensitization of tumor cells." (PMID 24326130, 2013). "Tivantinib demonstrated antiproliferative activity in several human cancer cell lines that constitutively express MET (IC50 = 0.30 to 0.66 μM), and showed significant antitumor activity in multiple xenograft tumor mouse models." (PMID 24260160, 2013). "Other conditional tumor suppressor genes identified in CRC and other cancers, include DCC, UNC5C, p75NTR and MET." (PMID 23874207, 2013). "Thus, MET may not only serve as a major determinant of cancer progression in terms of local growth and metastasis, but it may also be an important signaling regulator of responses to DNA damage that can “assist” tumor cells evading RT-induced cytotoxicity." (PMID 24378750, 2013). "Most notably, cabozantinib, a pan-tyrosine kinase inhibitor with high affinity for c-MET and VEGFR2, is being tested in a phase II clinical trial for recurrent GBM with encouraging tumor responses and acceptable toxicity." (PMID 23579692, 2013). "Mouse models with overexpression of MET induce basal-like tumors with signatures of WNT and epithelial to mesenchymal transition, suggesting that this pathway’s importance in tumor biology is conserved across species." (PMID 24025166, 2013). "Heterogeneous populations, including candidate CSC, are present in the MPE- tumor population, as reflected by the variable expression of CSC-biomarkers: c-MET, uPAR, MDR1, CD166, CD44, and ALDH." (PMID 24019906, 2013). "MET overexpression and its crosstalk with other receptors, such as EGFR, Her2, Her3 are also critical for tumor development." (PMID 23296269, 2013). "Concurrent inhibition of MET and VEGF signaling can slow tumor growth, decrease invasion and metastasis, and change invasive tumors into a shape with a ball-like appearance in certain models." (PMID 24213559, 2013).
tumor (continued). "However, the levels of VEGFR2 and MET were very low or undetectable in LuCaP 23.1 and C4-2B tumors, and because very little of the tumor tissue was available following cabozantinib treatment, we could not evaluate the on target effects by looking at decreases in phosphorylaiton of these targets." (PMID 24205338, 2013). "The most widely expressed tumor-specific protein in our cohort was GLUT1, positive in 20.3% of the cancers, followed by EGFR (17.4%), IGF-1R (12.8%), HER2 (10.4%), CAIX (9.5%), and MET (8.9%)." (PMID 22695343, 2012). "A panel of tumor-specific markers (GLUT1, EGFR, HER2, IGF1-R, MET, and CAIX) was in the present study able to 'detect' 45.5% of all cancers and 55.6% of ductal cancers." (PMID 22695343, 2012). "Including TfR, Mammaglobin, and MUC1 to the panel of highly tumor-specific markers GLUT1, MET, EGFR, IGF1-R, CAIX, and HER2 increased the detection rate from 45.5% to 49.8% (TfR), 56.4% (Mammaglobin), and 98.1% (MUC1), respectively." (PMID 22695343, 2012). "MET, a tyrosine kinase, and its ligand, hepatocyte growth factor (HGF), play a pivotal role in tumor cell proliferation, survival, and metastasis." (PMID 23554766, 2012). "MET tyrosine kinase and its ligand, hepatocyte growth factor (HGF), play a pivotal role in the activties of tumor cells." (PMID 23554766, 2012). "Specific inhibition of MET phosphorylation with small molecule inhibitors has demonstrated the capacity of counteracting the HGF induced effects in SCLC and other tumour models." (PMID 21847116, 2011). "Taken together, our results demonstrate that the c-MET FFPE assay can detect and quantify c-MET receptor levels in FFPE tumor specimens, and these measurements correlate well with measurements obtained by conventional methods." (PMID 21283737, 2011). "In clinical samples, total MET and p-MET overexpression were detected in 54% and 43% SCLC tumours (n=77), respectively." (PMID 21847116, 2011). "Novel antibody proximity-based assays were developed and used to detect and quantify total c-MET, total HGF, and HGF-c-MET ligand-receptor interactions in FFPE cell line and tumor tissue." (PMID 21283737, 2011). "Targeted knockdown of MET in human RMS cell lines decreases RMS cell proliferation in vitro and tumor burden in mouse xenograft models." (PMID 21253475, 2011). "This allows us to live-sort candidate CSC-fractions from the MPE-tumor mix on the basis of surface markers (CD44, c-MET, uPAR, MDR-1) or differences in xenobiotic metabolism (ALDH)." (PMID 19536353, 2009). "We then investigated the expression of ESR1/ERα and that of the five following top-ranked genes (MET, FOS, SNCG, IGFBP4, and BCL2) by RTQ-PCR on the initial set of 18 tumor samples (eight control and 10 TF)." (PMID 18928543, 2008). "With tumour tissue microarray (TMA) and phosphoantibody immunostaining, we also gained further insight into the role of c-MET/HGF signalling in SCLC biology and tumour invasion." (PMID 17667909, 2007). "The growth factors and receptor genes EMMRIN, MET, TGF-β, VEGF-A and EGF-R all demonstrated highly significant positive correlations with tumour grade (P<0.001)." (PMID 16465195, 2006). "The RR of poor long-term survival was 2.46 for multiple tumours, 2.22 for co-expression of RON and MET, 2.03 for RON expression alone, and 1.98 for tumour staging." (PMID 15870710, 2005). "In addition, it was recently shown that tumour hypoxia may cause an increased transcription of MET through the upregulation of the hypoxia inducible factor-1 (HIF-1), which has two binding sites on the MET promoter." (PMID 15266330, 2004).
tumor (continued). "Increasing evidence indicates that oncogenic drivers, including EGFR, ALK, KRAS, MET, RET, and BRAF, actively shape the tumor immune microenvironment (TIME) by regulating antigen presentation, immune cell infiltration, cytokine signaling, metabolic programs, and immune checkpoint expression." (PMID 42079655, 2026). "Dacomitinib, an EGFR inhibitor, reduces tumor viability and self-renewal in EGFR-amplified GBM, although its effectiveness is influenced by the PTEN status, Despite their initial promise, c-MET inhibitors such as onartuzumab and rilotumumab have failed to significantly improve survival outcomes." (PMID 40628732, 2025). "Furthermore, this review explores the significant tumor heterogeneity and cellular plasticity observed in NEBC and discusses its cell of origin and potential therapeutic targets (MET inhibitor or DLL3) identified by preclinical NEBC models." (PMID 40893664, 2025). "From the tumours, we extracted RNA and verified the expression of ETV1, ERG and MET using RT‐qPCR." (PMID 39374163, 2025). "By using a specific MET tyrosine kinase inhibitor in a humanised hepatocyte growth factor (HGF) mouse model, we also establish that MET activity is required for ETV1/ERG‐mediated tumour growth." (PMID 39374163, 2025). "In addition, MET amplifications have been reported in patients with ALK, ROS1, TRKA/B/C or RET fusion‐positive tumours at progression on TKI therapy." (PMID 40437874, 2025). "Our findings revealed that AS1411-SL1 chimeras specifically induced c-MET degradation in tumor cells without influencing c-MET level in normal cells, thereby demonstrating the tumor-targeting ability of the chimeras." (PMID 39744222, 2025). "Notably, some genes (e.g., MET, HSPA6, ID1, MECOM, POU2AF1, SFRP4, CDH1) exhibited expression predominantly in tumor cells and a limited number of other cell types." (PMID 40954493, 2025). "In contrast, docking analyses with four key anti-tumor targets: VEGFR2 (PDB ID: 3VO3), MET (PDB ID: 3DKC), RET (PDB ID: 2IVU), and Trk-A (PDB ID: 6PL3) revealed only weak interactions, including Pi-Anion, Pi-Alkyl, and Pi-Cation interactions, rather than strong hydrogen bonding." (PMID 40257021, 2025). "Moreover, MET inhibition leads to reduced release of cytokines and growth factors, rendering the TME less favorable to tumor growth." (PMID 40565798, 2025). "Moreover, the IHC scores of c-MET and MMP10 in CCA were highly positively correlated and significantly upregulated relative to tumor-adjacent tissues." (PMID 41048570, 2025). "In MET- and Axl-high MKN45 xenografts, the agent significantly inhibited tumor growth." (PMID 41011010, 2025). "In addition to promoting tumour progression through enhanced cell proliferation and migration, the HGF/MET pathway also modulates the function and infiltration of immune cells within the tumour microenvironment, thus contributing to immune evasion." (PMID 40599602, 2025). "Our findings underscore the significance of c-MET and AXL as major tumor growth pathways in CDC." (PMID 40921965, 2025). "Teliso-V, a MET-targeted ADC, combined with osimertinib, reported an ORR of 50% and a mPFS of 6.8 months in patients with MET overexpressed (MET 3 or higher staining in ≥25% tumor cells) EGFR-mutant NSCLC progression on osimertinib." (PMID 40470164, 2025). "This fusion protein acts as an aberrant transcription factor, upregulating the MET proto-oncogene receptor tyrosine kinase (MET) signaling pathway, which promotes tumor proliferation, angiogenesis, and early metastasis, making this axis a promising therapeutic target." (PMID 40894409, 2025). "In its Phase I trial in patients with advanced solid tumors, MRX34 demonstrated target engagement and tumor-suppressive activity (with downregulation of BCL2, MET, MYC) at tolerated doses, but the trial was ultimately discontinued due to immune-mediated adverse events." (PMID 41226828, 2025).